TNF (tumor necrosis factor)
Diseases named in the same sentence as TNF in open-access papers (continued):
Sharing a sentence is not in itself a finding about the gene and the disease.
age (14 papers, 2019 to 2025). A temporal measurement of the time period elapsed since an identifiable point in the life cycle of an organism. "Prior studies have demonstrated that inflammatory cytokines such as TNF-α and IL-1β can impair osteoblast function and promote osteoclast-mediated bone resorption, accelerating age-related bone loss." (PMID 41247564, 2025). "Importantly, the genetic or pharmacological ablation of TNF signaling in aged mice restores intestinal barrier integrity and reduces systemic inflammation, demonstrating a direct causal role of immune-derived TNF in age-related gut dysfunction." (PMID 41514897, 2025). "Resistance training has been reported to mitigate age-related chronic inflammation in skeletal muscle by reducing the expression of cytokines such as TNFα and IL-1β." (PMID 40529358, 2025). "Variations in genes involved in the regulation of inflammatory pathways, such as interleukins and tumor necrosis factor (TNF), are associated with attenuating age-related inflammation and preserving vascular integrity." (PMID 39725804, 2025). "Recent evidence suggests that age-related chronic inflammation is correlated with elevated levels of circulating biomarkers, such as TNF-alpha, IL-1beta, IL-6, COX-2, iNOS." (PMID 39286235, 2024). "Of note, existing anti-TNF-α therapy infliximab and other TNF-α inhibitors have been shown to prevent age-related bone loss in various conditions." (PMID 35360075, 2022).
alcoholic fatty liver disease (14 papers, 2010 to 2025). Lipid infiltration of the hepatic parenchymal cells that is due to alcohol abuse. "The results of KEGG enrichment analysis showed several pathways significantly enriched in the HFD group, including “cardiac muscle contraction,” “protein digestion and absorption,” “TNF signaling pathway,” and “non‐alcoholic fatty liver disease”." (PMID 41306337, 2025). "Increased TNF-α production and NF-κB activation were found in monocytes of patients with alcoholic steatohepatitis." (PMID 20827314, 2010). "In humans with alcoholic steatohepatitis, serum TNF-α, IL-6, and IL-8 levels are increased, and their levels correlate with markers of the acute-phase response, liver function, and clinical outcome." (PMID 20827314, 2010). "Notably, anti-TNFα drugs, such as pentoxifylline or infliximab, used in the treatment of alcoholic steatohepatitis have also been tested with various levels of success in the treatment of alcohol-related liver disease in humans." (PMID 38493749, 2024). "Moreover, berberine diminished inflammation and lowered the levels of TNF-α, IL-6, and IL-1β in rats with non-alcoholic fatty liver disease by regulating the TLR4/MyD88/NF-κB signaling pathway." (PMID 38790653, 2024). "Interestingly, although upregulation of TNF-R1 is observed in the livers of patients with alcoholic steatohepatitis, a recent in vitro study showed that free fatty acids sensitized HepG2 cells to TRAIL-mediated apoptosis, but not to cytotoxicity mediated by TNF-α." (PMID 20827314, 2010).
bone marrow failure (14 papers, 2010 to 2026). "While baseline TNF signaling is known to be important for normal HSC maintenance, excessive TNF-α signaling is associated with bone marrow failure and MDS." (PMID 29181334, 2017). "The molecular mechanisms underlying bone marrow failure remain unclear, although TNF has been described as damaging to hematopoiesis." (PMID 29963054, 2018). "Bone marrow failure is often refractory to treatment with tumour necrosis factor-alpha (TNF-alpha) inhibitors and additional treatment options are needed." (PMID 41866403, 2026). "The patient with bone marrow failure (patient 8) was treated with anti-tumor necrosis factor (TNF), aspirin, and prednisolone." (PMID 37312195, 2023). "One patient (Patient 39) had progressed from a normocellular marrow showing active maturing trilineage hematopoiesis to a markedly hypocellular marrow with trilineage failure despite being treated with anti-TNF agents for 4 years prior to bone marrow failure." (PMID 35095905, 2021). "Trilineage bone marrow failure progressed in 1 patient with quiescent inflammatory disease while on a TNF inhibitor (Patient 39)." (PMID 35095905, 2021). "Bone marrow failure is mostly unresponsive to TNF-α inhibitors." (PMID 40545182, 2025). "In summary, platelets regulate the immune responses of CD4+ and CD8+ T cells through mitochondrial energy metabolism, contributing to immune dysregulation and increased levels of IFNγ and TNFα, leading to the destruction of HSPCs and potential bone marrow failure." (PMID 40552264, 2025). "TNF-α and IFN-γ have been proposed as causative stress in bone marrow failure in aplastic anemia." (PMID 37627314, 2023). "TNF inhibitors, including etanercept, adalimumab, infliximab, and golimumab, are used in several autoinflammatory disorders, including the IEI deficiency of adenosine deaminase 2 (DADA2), in which cytopenias, either autoimmune or due to bone marrow failure (BMF), occur in 50% of patients." (PMID 36052091, 2022). "Key cytokines including interferon-gamma (IFN-γ) and tumor necrosis factor-alpha (TNF-α) play crucial roles in this immune dysregulation, influencing HSPCs and contributing to bone marrow failure." (PMID 40552264, 2025). "CD4+ Th1 cells play a significant role in the pathogenesis of bone marrow failure by secreting pro-inflammatory cytokines like IFN-γ and TNF-α, which mediate HSPC apoptosis." (PMID 40552264, 2025). "Chronic expression of cytokines, e.g., IFN-α, IFN-γ, TNF-α, TGF-β, contributes to acquired bone marrow failure in inflammation-mediated mouse models." (PMID 37627314, 2023). "In a study of 31 DADA2 patients, TNF inhibitors significantly reduced the incidence of ischemic events and other vasculitic manifestations but was not effective for immunodeficiency or bone marrow failure, requiring a HSCT." (PMID 36052091, 2022). "Bone marrow failure in MDS involves apoptosis induction, which may involve TNF-α; persistent BM dysplasia following benzene exposure has also been associated with TNF-α polymorphisms." (PMID 20126546, 2010).
Dengue hemorrhagic fever (14 papers, 2014 to 2024). A serious condition caused by Dengue virus infection. "In patients with Dengue hemorrhagic fever and hyperinflammation, doxycycline substantially reduces mortality in association with a significant reduction in serum concentrations of interleukin-6, TNFα and interleukin-1." (PMID 36689456, 2023). "THP-1 cells infected with dengue virus induced elevated levels of dengue hemorrhagic fever (DHF)-associated immunomediators such as interleukin (IL)-6, IL-8, interferon γ-induced protein-10 (IP-10), tumor necrosis factor alpha (TNFα) or IFNγ." (PMID 28788062, 2017). "TNF-alpha is thought to be primarily responsible for endothelial remodelling and plasma leakage in vivo during severe dengue infection; chymase also contributes to dengue virus-induced vascular leakage and it has been proposed as a predictive biomarker of dengue haemorrhagic fever." (PMID 39768136, 2024). "Moreover, TNF-α has been shown to enhance vascular hyperpermeability in dengue hemorrhagic fever." (PMID 31491031, 2019). "A previous study demonstrated that in dengue hemorrhagic fever, most activated T cells had an inflammatory profile, with production especially of IFN-γ and TNF-α, but they were less cytotoxic, with a low expression of CD107a." (PMID 33525328, 2021). "Increased levels of TNF-α, IL-1β, IL-4, IL-6, IL-8, IL-13, IL-15, macrophage migration inhibitory factor (MIF), and chemokines CCL2, CCL4, CCL5, and CXCL10 (IP-10) among others, have been reported in patients with dengue hemorrhagic fever (DHF) when compared to dengue fever (DF)." (PMID 29986388, 2018). "In line with that, it is the study conducted by Soundravally and colleagues, who found increased levels of TNF-α and malondialdehyde (MDA), a biomarker of oxidative stress, in the plasma of patients with dengue hemorrhagic fever (DHF) and dengue shock syndrome (DSS)." (PMID 37457689, 2023).
diffuse large B-cell lymphoma (14 papers, 2009 to 2025). "It has been suggested that long-term therapy with immunosuppressive drugs and TNF inhibitor cause immunosuppression and increase the incidence of Epstein-Barr virus (EBV)—positive lymphomas (i.e., diffuse large B-cell lymphoma (DLBCL))." (PMID 33478454, 2021). "Among them, IL-10 -3575 A > T and TNF-α-308 G > A SNPs were reported to be associated with NHL, especially in diffuse large B-cell lymphoma (DLBCL) by several different groups." (PMID 26108796, 2015). "We also previously reported the association between the pro-inflammatory cytokine, tumor necrosis factor (TNF) G-308A promoter polymorphism with NHL and specifically with diffuse large B-cell lymphoma (DLBCL), a finding also confirmed in large consortial efforts." (PMID 22096508, 2011). "We confirmed the association between TNF/LTA on chromosome 6p21.3 with NHL and found the LTA rs2844484 SNP most significantly and specifically associated with the major subtype, diffuse large B-cell lymphoma (DLBCL) (p-trend = 0.001)." (PMID 19390683, 2009). "It is noteworthy that mice with miR-155 overexpression in a B cell-specific manner develop high-grade B-cell lymphoma resembling diffuse large B-cell lymphoma (DLBCL), likely owing to the effect of miR-155 on SHIP1, which promotes TNFα-dependent cell proliferation." (PMID 31472685, 2019).
gallbladder cancer (14 papers, 2012 to 2024). "Hong demonstrated that CCR7 mediated the TNF-α-induced lymphatic metastasis of gallbladder cancer through the “ERK1/2-AP-1” and “JNK-AP-1” pathways." (PMID 39127853, 2024). "After cultured with aprepitant for different time, gallbladder cancer cells generated more inflammatory cytokines including IL‐6, IL‐1β and TNF‐α." (PMID 37221457, 2023). "Autocrine TNF-α was reported to act as a tumor promoter gene by promoting gallbladder cancer cell proliferation via the AKT/NF-κB/Bcl-2 pathway." (PMID 37291206, 2023). "TNF-α is a key inflammatory cytokine responding to chronic inflammation which is a major carcinogenic mechanism of gallbladder cancer." (PMID 33753990, 2021). "In one study it was noted that the silencing of TNF-α in a cell line of the gallbladder cancer decreased cell proliferation and invasion by an autocrine effect, influencing the signaling pathways of TNF-α/NF-kB/AKT/ Bcl-2 in these cells." (PMID 32283655, 2020). "In gallbladder carcinoma, tumor necrosis factor-α (TNF-α) promotes lymph node metastasis through nuclear factor-κB-mediated." (PMID 27911876, 2017). "Tumor necrosis factor-alpha (TNF-α), a key player in cancer-related inflammation, was recently demonstrated to be involved in the lymphatic metastasis of gallbladder cancer (GBC)." (PMID 26992854, 2016). "In conclusion, in the present study, we verify the biological behavior of gallbladder cancer cell-derived TNF-α." (PMID 24676340, 2014). "Our data provide evidence that autocrine TNF-α plays a role as a tumor promoter gene in gallbladder cancer cells, possibly by promoting proliferation and invasion through autocrine mechanisms." (PMID 24676340, 2014). "We provide evidence that the reduction of autocrine TNF-α in gallbladder cancer cells can exert inhibitory effects on the ability of the cells to grow and migrate in vitro." (PMID 24676340, 2014). "TNF-α is associated with HCC, colitis-associated cancer, and gallbladder cancer." (PMID 37291206, 2023). "This provides further evidence that targeting TNF-α and its intracellular pathways may prove useful in the treatment of gallbladder cancer." (PMID 24676340, 2014). "We determined whether TNF-α was expressed in two different gallbladder cancer cell lines (NOZ and SGC-996)." (PMID 24676340, 2014). "Thus, we speculated that TNF-α might promote lymphatic metastasis of gallbladder cancer through upregulation of CCR7." (PMID 27009073, 2016). "Therefore, we hypothesized that TNF-α might promote lymphatic metastasis of gallbladder cancer via upregulation of CCR7." (PMID 27009073, 2016). "However, whether gallbladder cancer cells produce autocrine TNF-α, and whether gallbladder cancer cell-derived TNF-α affects the biological behavior of the cells, remain unresolved issues." (PMID 24676340, 2014). "Thus, in the present study, we examined various gallbladder cancer cell lines expressing different levels of TNF-α in order to determine the effects of TNF-α on gallbladder cancer proliferation, invasion, metastasis and apoptosis, as well as the underlying mechanisms involved." (PMID 24676340, 2014). "Nuclear factor (NF-κb) -VEGF-C pathway participates in the lymphangiogenesis of gallbladder carcinoma, and VEGF-C is activated in response to proinflammatory cytokines such as TNF-α." (PMID 36105188, 2022). "TRAIL has been previously identified as important markers in gallbladder cancer survival, TRAIL and TNF-α are cytokines that bind to death receptors and recruit CASP-8 which triggers cell death inducing apoptosis in cancer cells." (PMID 33574564, 2021). "Moreover, it was demonstrated that a strong relation between TNF-α levels and vascular endothelial growth factor D (VEGF-D) expression in samples of lymphatic metastasis from gallbladder cancer patients." (PMID 31137684, 2019).
gallbladder cancer (continued). "In addition, using siRNA targeting TNF-α, the vector, pGPU-GFP-siTNF-α, was constructed and then transfected into the SGC-996 cells (gallbladder cancer cell line) which express high levels of endogenous TNF-α." (PMID 24676340, 2014). "We also examined the expression of Bax, which can promote the apoptosis of gallbladder cancer cells, and found that TNF-α silencing did not significantly increase the expression of the Bax gene." (PMID 24676340, 2014). "We also examined the expression of the Bax gene, which can promote the apoptosis of gallbladder cancer cells, and found that TNF-α silencing did not significantly increase the expression of the Bax gene P>0.05." (PMID 24676340, 2014). "As the role of autocrine TNF-α in human gallbladder cancer has not yet been elucidated, the present study examined the expression of TNF-α in gallbladder cancer-derived cell lines." (PMID 24676340, 2014). "Besides, researchers have found that TNF-α could upregulate VEGFC expression, promoting lymphangiogenesis and lymphatic metastasis in gallbladder cancer." (PMID 37124061, 2023).
gastric adenocarcinoma (14 papers, 2013 to 2025). "Studies have shown that CAPE can inhibit the activation of NF-κB and AP-1, as well as the secretion of IL-8 and TNF-α, in gastric adenocarcinoma cells induced by H. pylori." (PMID 40944192, 2025). "A persistent stomach infection with H. pylori induces secretion of proinflammatory cytokines, including IL-1β, IL-6, IL-8, and TNF-α, which are closely linked to MALT-lymphoma and gastric adenocarcinoma." (PMID 30646625, 2019). "The cytokine gene polymorphisms including polymorphisms of the IL-1, TNF-α and IFN-γ have been also related with H. pylori-associated gastric adenocarcinoma and PU." (PMID 23467184, 2013). "In a gastric adenocarcinoma cell model of H. pylori infection, propolis reduces the expression levels of various pro-inflammatory cytokines (including IL-8, IL-12, IL-1β) and inflammatory markers (such as TNF-α, COX-2, iNOS)." (PMID 40944192, 2025). "Some isolated compounds (cassaine diterpenoid dimers) from this family contribute to anticancer activity by decreasing apoptosis inhibitors or increasing apoptosis inducers; this leads to tumor necrosis factor (TNF)-related apoptosis-inducing ligand resistance in human gastric adenocarcinoma cells." (PMID 27110278, 2016). "Moreover, the alkaloid cryptolepine isolated from the methanol extract prepared from the whole plant and tested at concentrations of 1.25, 2.5 and 5 μM was able to solve tumor necrosis factor (TNF)-related apoptosis-inducing ligand resistance in human gastric adenocarcinoma (AGS) cell lines." (PMID 39478959, 2024). "To assess the anticancer effects of ainsliadimer A, we treated gastric adenocarcinoma BCG-823 cells with ainsliadimer A alone, TNF-α alone or with a combination of ainsliadimer A and TNF-α for a period of 24 h." (PMID 25813672, 2015). "The majority of our cohort consisted of conventional gastric adenocarcinomas, in which AFP was seldom elevated; thus, the absence of a TNF-α–AFP relationship simply reflects that AFP was not a prevalent tumor marker in these patients." (PMID 40299527, 2025).
gram-negative bacterial infections (14 papers, 2011 to 2025). Infections caused by bacteria that show up as pink (negative) when treated by the gram-staining method. "Since TNF derived from MCs (unlike other cell types) has been associated to a protective response against gram-negative bacterial infections in mice, the impaired production of TNF resulted in an increased mortality in R6/1 mice and Wsh mice reconstituted with R6/1 BMMCs after a sub-lethal LPS dose." (PMID 32220257, 2020). "Other studies have shown that IL-4 and TNF-α have a dual role in resisting Gram-negative bacterial infections in the organism." (PMID 38764854, 2024). "The Imd pathway controls anti-bacterial peptide gene expression in the fat body in response to gram-negative bacterial infections and the pathway is suggested to be similar to the mammalian TNF-α pathway." (PMID 34659116, 2021). "It has been suggested that TNF-α is involved in acute inflammatory responses against Gram-negative bacterial infections, as well as other infectious agents." (PMID 27051668, 2016). "Based on the results, the serum pro-inflammatory cytokine measurements, especially the TNF-α concentration, could be used as an early prognostic factor for Gram-negative bacterial infection as well as the serum iron concentration." (PMID 33540888, 2021). "While TNF-α is an endogenous pro-inflammatory cytokine particularly involved in autoimmune disorders, LPS, as a component of bacterial membranes, is widely used to experimentally mimic gram-negative bacterial infections." (PMID 29792190, 2018). "Our study confirmed that many of these cellular pathways, including the INFα/β, TNF-α, MAPK, PI3 K, NF-κB, and TLRs, and their cross-talked axes, are activated by Gram-negative bacterial infections in the plaque microenvironment." (PMID 40275124, 2025).